CD4 (CD4 molecule)
Diseases named in the same sentence as CD4 in open-access papers (continued):
Sharing a sentence is not in itself a finding about the gene and the disease.
experimental autoimmune encephalomyelitis (continued). "In the mouse, IL-6 mainly induce the differentiation of naive CD4-positive T cells into Th17 cells, whereas anti-IL-6 therapy effectively suppresses the onset of experimental autoimmune encephalomyelitis via the inhibition of the development of autoantigen-specific Th17 cells." (PMID 36389702, 2022). "For experimental autoimmune encephalomyelitis mice, these infiltrating microglial cells or monocytes with overexpressed CD93 tend to cause T cells apoptosis, which greatly immunosuppressed functional CD4+ and CD8+ T cells." (PMID 36006582, 2022). "Autoreactive CD4+ T cells, including IFNγ-secreting T helper (Th) 1, IFNγ/IL‐17-secreting Th17, or IFNγ/GM‐CSF-secreting cells, play an important role in MS, which is supported by data from the experimental autoimmune encephalomyelitis (EAE) mouse models." (PMID 35488271, 2022). "We synthesized the AP-conjugated cytoplasmic domain of CTLA-4, AP-ctCTLA-4, which showed significant suppression of IL-17A and induction of Foxp3 in vitro as well as the alleviation of experimental autoimmune encephalomyelitis (EAE), with reduced levels of pathogenic IL-17A+GM-CSF+ CD4 T cells." (PMID 34452095, 2021). "Here we show that OPTN is upregulated in human and mouse DC maturation, and that deletion of Optn in mice via CD11c-Cre attenuates DC maturation and impairs the priming of CD4+ T cells, thus ameliorating autoimmune symptoms such as experimental autoimmune encephalomyelitis (EAE)." (PMID 34707127, 2021). "In this study, we showed that Cd226−/− mice were resistant to myelin oligodendrocyte glycoprotein peptide 35-55 (MOG35−55)-induced experimental autoimmune encephalomyelitis (EAE) with highly expressed IL-10+CD4+ T cells and downregulated IL-17A+CD4+ T cells when compared with wild-type (WT) mice." (PMID 32983109, 2020). "Here, we show that the mice lacking miR17-92 specifically in CD4+ T cells or both total miR106b-25 and miR17-92 in CD4+ T cells (double knockout) are protected from Experimental Autoimmune Encephalomyelitis (EAE) development while depletion of miR106b-25 only does not influence EAE susceptibility." (PMID 32973667, 2020). "MHV-induced acute neuroinflammation occurs due to direct glial cell dystrophy instigated by central nervous system (CNS)-resident microglia and astrocytes, in contrast to peripheral CD4+T cell-mediated myelin damage prevalent in the experimental autoimmune encephalomyelitis (EAE) model of MS." (PMID 32477069, 2020). "Experimental autoimmune encephalomyelitis is a useful experimental model to compare the function and behavior of CD4+ T cells, including Treg, retrieved from the site of autoimmune inflammation (in this case the CNS) versus those from the secondary lymphoid organs of the same mouse." (PMID 29535709, 2018). "In this study, lower RORγT and higher GATA-3 transcription factor expression levels in CD4+ cells were also detected in experimental autoimmune encephalomyelitis mice treated with hMSCs, which suggests that the Th17 phenotype is restrained while the Th2 subset is favored by the treatment with hMSCs." (PMID 30254638, 2018). "Indeed, central nervous system tissue and encephalitogenic CD4 T cells during experimental autoimmune encephalomyelitis were characterized by massive changes in Interferome transcription." (PMID 28827704, 2017). "In contrast, PD-L1−/− mice appeared normal but were susceptible to experimental autoimmune hepatitis (induced by accumulation of antigen-activated CD8+ T cells in the liver) and experimental autoimmune encephalomyelitis (induced by myelin-reactive CD4+ Th1 cells)." (PMID 29255458, 2017). "Moreover, blocking IL-7 signaling in myelin-specific CD4 T cells by αIL-7Rα significantly delays experimental autoimmune encephalomyelitis (EAE) onset and reduces disease severity." (PMID 27912762, 2016).
experimental autoimmune encephalomyelitis (continued). "Indeed, IFN-γ plays an important role in apoptosis induction or reduction of CD4+ T cells during infectious diseases, in response to tumors and in the experimental autoimmune encephalomyelitis." (PMID 27403034, 2016). "Previous studies showed MSCs inhibited experimental autoimmune encephalomyelitis- (EAE-) derived CD4+ T cell activation by suppressing STAT3 phosphorylation via CCL2, and CCL2−/− MSCs could not ameliorate disease and decrease Th17 cells in EAE mice." (PMID 25918734, 2015). "Increased expression of co-stimulatory molecules has usually been associated with an immune activating phenotype of APCs, but recently expression of B7 (CD80/CD86) on murine B cells was shown to be central to regulation of CD4+CD25high Tregs in experimental autoimmune encephalomyelitis." (PMID 25401487, 2014). "CD4+ T cells activated either in the presence of IL-6 and TGF-β, or IL-6, IL-1 and IL-23 both produce IL-17, but those skewed with TGF-β appear to be less inflammatory and fail to transfer susceptibility to experimental autoimmune encephalomyelitis (EAE)." (PMID 24475259, 2014). "Mice with targeted deletion of STAT3 in CD4+ T-cells do not develop experimental autoimmune uveitis (EAU) or experimental autoimmune encephalomyelitis (EAE), in part, because they cannot generate pathogenic Th17 cells." (PMID 22238646, 2012). "Interestingly, mice with CARMA1-deficient CD4 T cells exhibit resistance to experimental autoimmune encephalomyelitis (EAE), yet their T cells do not show impaired expression of RORγt, Ahr, IRF4, or STAT3/STAT5 signaling." (PMID 40370445, 2025). "We hypothesized that by exploiting the dependency of CD4+ T cells on extracellular Asn by systemically depleting Asn bioavailability, we could modulate the severity CD4+ T cell mediated pathologies, such as experimental autoimmune encephalomyelitis (EAE)." (PMID 40661510, 2025). "Therefore, treatment with the combination of IL-2 and a calcineurin inhibitor can induce Treg expansion while inhibiting the expansion of inflammatory cytokine-producing CD4+ T cells, resulting in an additive effect in experimental autoimmune encephalomyelitis." (PMID 38665907, 2024). "Experimental autoimmune encephalomyelitis (EAE) is a commonly used animal model of MS in which disease is induced by immunization of animals with myelin-derived antigenic peptides together with adjuvant or by adoptively transferring pre-activated myelin-specific CD4+ T cells in naïve recipients." (PMID 28289410, 2017). "Here, we report that DKO TH2-high carrying autoantigen-specific TCR (2D2) develop atypical spontaneous experimental autoimmune encephalomyelitis (EAE), with CD4+ T cells simultaneously producing IL-4 and GM-CSF, directly causing neuroinflammation." (PMID 41577662, 2026). "Here, using experimental autoimmune encephalomyelitis (EAE), a murine model of MS, we found a marked expansion of effector CD4+ T cells in the lungs of EAE mice." (PMID 42106839, 2026). "In experimental autoimmune encephalomyelitis (EAE), an animal model of MS, myelin specific CD4 autoreactive T cells are activated in peripheral lymph nodes, migrate to CNS and get reactivated by antigen presenting cells in the CNS." (PMID 40457355, 2025). "As demonstrated in the experimental autoimmune encephalomyelitis (EAE) disease model, the migration of β7+CD4+ T cells to the gut and the subsequent interaction with gut microbiota potentiated their encephalitogenic potential." (PMID 40709181, 2025). "In experimental autoimmune encephalomyelitis (EAE) model and in vitro, IFN-γ induced the conversion of CD4+ CD25– T cells to CD4+ Tregs." (PMID 41383600, 2025). "In another study, Themis has been shown to modulate the severity of experimental autoimmune encephalomyelitis (EAE) by regulating TCR-independent signaling and the production of pro-inflammatory cytokines in CD4+ T cells, mainly polarized TH1 cells." (PMID 40777021, 2025).
experimental autoimmune encephalomyelitis (continued). "It has been claimed in a previous animal study that CD4+EOMES+T‐cells were required for the augmentation of CNS inflammation on adoptive transfer and the induction of chronic stage in experimental autoimmune encephalomyelitis mice." (PMID 37850654, 2024). "In particular, within the experimental autoimmune encephalomyelitis (EAE) model, B cells have been shown to interact with CD4+ T cells, initiating an adaptive immune response directed against myelin antigens." (PMID 38399365, 2024). "In MS and its animal model experimental autoimmune encephalomyelitis, MSC injection was shown to alter the differentiation of CD4+T cells." (PMID 39010157, 2024). "In another study of experimental autoimmune encephalomyelitis (EAE), cortactin knockout mice exhibited decreased incidence, disease severity, and infiltration of the central nervous system by CD4+ T cells." (PMID 37485352, 2023). "In a mouse model of experimental autoimmune encephalomyelitis (EAE), IL-23 drives the expansion of the IL-17A+ CD4+ T-cell population." (PMID 36763636, 2023). "On the other hand, cpTLR-i was not able to suppress the induction of Th17 cells in our in vitro culture with CD4 T cells alone, although other studies reported an intrinsic role of TLR signaling in Th17 cells and experimental autoimmune encephalomyelitis." (PMID 37215126, 2023). "Experimental autoimmune encephalomyelitis (EAE), featured by CD4+ T cell-mediated inflammation and demyelination, is an ideal model for human MS." (PMID 36160384, 2022). "It has been reported that N. brasiliensis infection protects against experimental autoimmune encephalomyelitis (EAE) via increased IL-5 levels and subsequent increases in eosinophils and CD4+CD25+ Tregs." (PMID 35625566, 2022). "Here, we show that experimental autoimmune encephalomyelitis (EAE), induced by the adoptive transfer of encephalitogenic CD4+ Th17 cells, was more severe, and less likely to remit, in middle-aged compared with young adult mice." (PMID 35511417, 2022). "In experimental autoimmune encephalomyelitis, CD8+CD28- Tregs inhibited the secretion of IFN-g by myelin oligodendrocyte glycoprotein-specific CD4+ T cells." (PMID 34335631, 2021). "Since MOG-reactive CD4+ T cells are the most important cell type for the induction of the neuroinflammatory disease experimental autoimmune encephalomyelitis (EAE), we examined the influence of MOG-expression on CD4+ T cell tolerance." (PMID 34149706, 2021). "In vivo or in vitro exposure to 17β-estradiol increases CD4+CD25+ T cell numbers and FoxP3 expression in Experimental Autoimmune Encephalomyelitis (EAE)." (PMID 33746959, 2021). "In disease models of F. tularensis pneumonia and experimental autoimmune encephalomyelitis (EAE), inhibition of GSK3β with lithium reduces the numbers of IL17A+CD4+ and IFNγ+CD4+ but spares Tregs in the lungs and spinal cords of mice, respectively." (PMID 32850361, 2020). "In vitro, we studied the capacity of MGL to mediate apoptosis of experimental autoimmune encephalomyelitis (EAE)-derived T cells and mouse CD4+ T cells." (PMID 31248427, 2019). "Previously we have shown that HINT1/Hsp70 treatment induced regulatory NK cells ameliorating experimental autoimmune encephalomyelitis (EAE) course and CD4+ T cells proliferation." (PMID 31362466, 2019). "Several studies have demonstrated that CD4+LAP+ T cells suppress diseases such as colitis, lupus, atherosclerosis and experimental autoimmune encephalomyelitis (EAE) in animal models." (PMID 29789580, 2018). "Relapsing experimental autoimmune encephalomyelitis was induced in ABH mice and immune cell depletion was therapeutically applied using mouse CD52 or CD4 (in conjunction with CD8 or CD20) depleting monoclonal antibodies." (PMID 27925187, 2017).
experimental autoimmune encephalomyelitis (continued). "Traditionally, Th1 cells (interferon-γ-producing CD4+ T cells) driven by interleukin 12 (IL12) were considered to be the encephalitogenic T cells in MS and experimental autoimmune encephalomyelitis (EAE), an animal model of MS." (PMID 22203863, 2012). "This presentation of the viral antigen must be processed, which allows the CD4+ T cells to be engaged with class II MHC to induce injury, the common mechanism of injury presumed to be present in experimental autoimmune encephalomyelitis." (PMID 22666554, 2012). "MACS-sorted naïve CD4+ T cells were either applied on healthy CNS slices or intravenously injected into RAG1 -/- mice, which were affected by experimental autoimmune encephalomyelitis (EAE)." (PMID 21978405, 2011). "Surprisingly, CD4-restricted ablation of RelA (but not c-Rel) provides protection against experimental autoimmune encephalomyelitis (EAE),a model of autoimmune disease that heavily relies on the presence and function of pathogenic Th17 cells." (PMID 40370445, 2025). "It was found that the m6A-modifying demethylase ALK-BH5 promotes IFN-γ and CXCL2 mRNA stability in CD4+ T cells, which in turn enhances CD4+ T cell pathogenicity in experimental autoimmune encephalomyelitis (EAE), whereas the demethylase FTO does not function." (PMID 39544933, 2024). "Prmt5 inhibition or deletion in CD4+ T cells has been reported to ameliorate experimental autoimmune encephalomyelitis (EAE), but the detailed molecular mechanisms have not yet been elucidated." (PMID 37533053, 2023). "It has been proven by both experimental autoimmune encephalomyelitis (EAE) model and MS treatment studies that CD4+ T cells that migrate to the CNS are activated by antigen-presenting cells and direct leukocytes such as T and B cells and macrophages to initiate myelin damage." (PMID 36765289, 2023). "Experimental autoimmune encephalomyelitis (EAE), which serves as an animal model of MS, is also induced by the activation of myelin reactive CD4+ T cells and their subsequent migration in the CNS, where they mediate inflammatory responses, resulting in demyelination and neurodegeneration." (PMID 35587373, 2022). "Here we show that in mice lacking P2Y10 in the CD4 T cell compartment, the severity of experimental autoimmune encephalomyelitis and cutaneous contact hypersensitivity is reduced." (PMID 34815397, 2021). "Experimental autoimmune encephalomyelitis (EAE), a well-established murine model that replicates key pathological features of MS, is induced by active immunization with myelin proteins or transfer of encephalitogenic CD4+ T cells." (PMID 29099057, 2017). "CD73-/- mice are resistant to induction of experimental autoimmune encephalomyelitis (EAE), even though CD4 T cells from CD73-/- mice secrete more proinflammatory cytokines than WT mice and are able to induce EAE when transferred into naïve CD73-/- T cell-deficient recipients." (PMID 26919582, 2016). "In an important article published in Nature Medicine, Liu and colleagues described a novel CD4+ FoxA1+ regulatory T (Treg) cell population as distinct regulators of relapsing-remitting multiple sclerosis (RRMS) and experimental autoimmune encephalomyelitis (EAE)." (PMID 25896927, 2015). "CD4+ T cells lacking miR-21 were shown to exhibit a specific Th17 cell defect affecting the transforming growth factor-β pathway during experimental autoimmune encephalomyelitis in vivo." (PMID 26575387, 2015). "The most widely used model for MS, experimental autoimmune encephalomyelitis, is an autoantigen-immunized disease that can be transferred to naive animals with CD4+ T cells, but not with antibodies." (PMID 26500654, 2015). "Although IL9 was previously regarded as one of the Th2 type cytokines, it was recently reported that IL9-producing CD4+T cells can induce neuroinflammation in certain conditions and that Th17 cells can produce IL9, which exacerbates experimental autoimmune encephalomyelitis." (PMID 25919001, 2014).
experimental autoimmune encephalomyelitis (continued). "This correlation might also explain the limited success of mannosylated antigens in animal models like experimental autoimmune encephalomyelitis (EAE), which is known to be mediated mainly by CD4+ T cells." (PMID 25137039, 2014). "Immunization with myelin oligodendrocyte glycoprotein (MOG) induces experimental autoimmune encephalomyelitis (EAE), a mainly CD4+ T-cell-mediated disease, although CD8+ T cells may play a significant role in demyelination." (PMID 24083230, 2013). "In spontaneous experimental autoimmune encephalomyelitis (EAE) secondary to Treg dysfunction, the adoptive transfer of CD4+ T cells from either wild-type or IL-2−/− KO mice conferred protection from EAE, whereas adoptive transfer of CD4+ T cells from IL-2Rα−/− KO mice did not." (PMID 22984435, 2012). "α1, α2, β1, β2, γ3 and δ were identified in CD4+ T cells from the type-1 diabetic NOD (non-obese diabetic) mice whereas in CD4+ T cells from an experimental autoimmune encephalomyelitis (EAE) mouse model α1, β1, γ2 and ε were examined but not detected." (PMID 22927941, 2012). "These cells, particularly CD4+LAP+ T cells expressing membrane‐bound TGF‐β, may migrate from the intestinal mucosa to peripheral lymphoid organs, contributing to immune regulation, as observed in experimental autoimmune encephalomyelitis." (PMID 40745935, 2026). "In an experimental autoimmune encephalomyelitis mouse model of MS, both dCLN resection and MLV ablation lowered cluster of differentiation 4 (CD4) T cell infiltration of the spinal cord parenchyma, whereas they increased the number of CD4 T cells in the meninges, leading to milder neuropathology." (PMID 36380442, 2024). "Furthermore, induction of experimental autoimmune encephalomyelitis with a single CD4 T cell epitope does not reflect the breadth of epitopes observed in the clinic." (PMID 39330967, 2024). "Interestingly, CD4+ T cells needed to be primed by NLRP3 inflammasome-sufficient antigen-presenting cells to upregulate chemotactic proteins such as osteopontin, CCR2, and CXCR6 in experimental autoimmune encephalomyelitis (EAE)." (PMID 36766797, 2023). "Similarly, CD4+ T cells can be found in the DRG at the onset of an experimental autoimmune encephalomyelitis (EAE) model and yet are absent at the chronic time point, suggesting that CD4+ cells exhibit transient expression in the DRG." (PMID 34884605, 2021). "We induced experimental autoimmune encephalomyelitis (EAE) in mice constitutively deleted for the miR106b-25 cluster, in mice lacking the miR17-92 in CD4+ T cells, and in mice with both mutations, to try to dissect the contribution of these miRNA families to neuroinflammation." (PMID 32973667, 2020). "Interestingly, antigen-nonspecific T cells, including myelin oligodendrocyte glycoprotein (MOG) tetramer–negative CD4+ Th17 cells, also infiltrate the central nervous system (CNS) in significant proportions and exacerbate experimental autoimmune encephalomyelitis (EAE) pathogenesis." (PMID 37121980, 2023). "However, in a study investigating experimental autoimmune encephalomyelitis (EAE), an MS model in which pathology is driven mainly by CD4+ T cells, an increased P2RY12 expression was found during the remission phase, which indicates that the regulation of P2RY12 may be more complex." (PMID 30297998, 2018).